UBE3B (ubiquitin protein ligase E3B)
Diseases named in the same sentence as UBE3B in open-access papers:
UBE3B is named in the same sentence as 38 diseases in open-access papers, as found by Europe PMC text mining. Sharing a sentence is not in itself a finding about the gene and the disease. The quoted sentences say what the papers report.
Kaufman oculocerebrofacial syndrome (6 papers, 2014 to 2025). "In this review article, we summarize recent findings on brain-expressed HECT-type E3 UBE3 ligases and their murine orthologues, comprising Angelman syndrome UBE3A, Kaufman oculocerebrofacial syndrome UBE3B and autism spectrum disorder-associated UBE3C." (PMID 33182779, 2020). "We showed here that bovine PIRM syndrome, which resembles human Kaufman oculocerebrofacial syndrome, is associated with a UBE3B mutation." (PMID 25306138, 2014). "Protein ubiquitination may be associated with myopia development, because a loss-of-function mutation in the E3 ubiquitin-protein ligase UBE3B was shown to cause Kaufman oculocerebrofacial syndrome, which includes myopia as one its prominent features." (PMID 30300342, 2018). "Kaufman oculocerebrofacial syndrome (KOS) (OMIM #244450) is a very rare autosomal recessive disorder caused by pathogenic biallelic variants in the UBE3B gene." (PMID 41318572, 2025). "The condition was later named Kaufman oculocerebrofacial syndrome (KOS), and in 2012, biallelic loss-of-function variants in UBE3B were identified as the underlying molecular cause." (PMID 41318572, 2025). "We report a 12-month-old infant with Kaufman oculocerebrofacial syndrome (KOS) due to a homozygous UBE3B splice site variant (c.1741 + 2T > C)." (PMID 41318572, 2025). "Finally, deletions of CYP26A1 (MIM 602239) and CYP26C1 (MIM 608428) have previously been implicated in both nonsyndromic bilateral and unilateral optic nerve aplasia, and mutations in UBE3B (MIM 608047) have been described in Kaufman Oculocerebrofacial Syndrome (MIM 244450)." (PMID 32040484, 2020). "Here, we describe an infant presenting with classical clinical features of Kaufman oculocerebrofacial syndrome (KOS) and a rare homozygous splice site variant in UBE3B (c.1741 + 2T > C)." (PMID 41318572, 2025). "Kaufman oculocerebrofacial syndrome (KOS; OMIM #244450)is a rare autosomal recessive disorder caused by pathogenic biallelic variants in UBE3B, characterized by craniofacial dysmorphism, global developmental delay, hypotonia, and multisystem anomalies." (PMID 41318572, 2025). "Bovine PIRM resembles the human autosomal recessive neurodevelopmental disorder Kaufman oculocerebrofacial syndrome, also known as blepharophimosis-ptosis-intellectual disability syndrome (MIM 615057, MIM 244450), caused by ubiquitin protein ligase E3B (UBE3B) mutations." (PMID 25306138, 2014).
lymphoma (5 papers, 2020 to 2025). A malignant (clonal) proliferation of B- lymphocytes or T- lymphocytes which involves the lymph nodes, bone marrow and/or extranodal sites. "The mechanism of TRIB3 has been investigated; previous studies have shown that TRIB3 promotes MYC-associated lymphoma development through suppression of UBE3B-mediated MYC degradation." (PMID 35726370, 2022). "Moreover, a loss-of-function mutation of UBE3B (R346Q) is found in MYC-associated lymphoma patients and impedes MYC degradation." (PMID 33298911, 2020). "TRIB3 interacted with MYC to suppress E3 ubiquitin ligase UBE3B-mediated MYC degradation, which induced the enhanced expression of MYC, causing the proliferation of lymphoma cells." (PMID 35668944, 2022). "We found that TRIB3 interacts with MYC to suppress E3 ubiquitin ligase UBE3B-mediated MYC ubiquitination and degradation, which causes high proliferation and self-renewal of lymphoma cells." (PMID 33298911, 2020). "Mechanistically, TRIB3 interacts with MYC to suppress E3 ubiquitin ligase UBE3B-mediated MYC ubiquitination and degradation, which enhances MYC transcriptional activity, causing high proliferation and self-renewal of lymphoma cells." (PMID 33298911, 2020). "Ube3b overexpression reduced the enlarged spleens and LNs and reduced the number of Ki-67-positive cells in the spleens of lymphoma mice, which was reversed by TRIB3 overexpression." (PMID 33298911, 2020). "By examining the endogenous interactions with Co-IP, we found that MYC, UBE3B, and MAX (also known as MYC-associated factor X) formed the heterotrimer in lymphoma cells." (PMID 33298911, 2020). "In addition, a recent study demonstrated that suppression of the E3 ubiquitin ligase UBE3B-mediated MYC ubiquitination and degradation caused by the integration of TRIB3 with MYC is associated with high proliferation and self-renewal of lymphoma cells." (PMID 33652974, 2021). "Thus, high MYC expression may be mainly caused by a decreased interaction of UBE3B and MYC, which is induced by elevated TRIB3 expression in lymphoma cells." (PMID 33298911, 2020). "Taken together, these data indicated that K427 of MYC is critical for UBE3B-catalyzed MYC ubiquitination and the functions of TRIB3 in promoting lymphoma cell growth are dependent on T58 phosphorylation of MYC." (PMID 33298911, 2020). "The pathophysiological relevance of UBE3B, TRIB3 and MYC is further demonstrated in human lymphoma." (PMID 33298911, 2020). "In comparison with the benign LN tissues, most lymphoma specimens showed high expression of TRIB3 but not UBE3B." (PMID 33298911, 2020). "We evaluated the effects of UBE3B and TRIB3 on lymphoma development in MycEμ mice." (PMID 33298911, 2020). "Indeed, UBE3B overexpression reduces MYC abundance and suppresses its transcriptional activity, resulting in lymphoma inhibition." (PMID 33298911, 2020). "Interestingly, our work indicates that UBE3B may not represent a viable drug target because UBE3B deletion in lymphoma cells decreases tumor cell proliferation." (PMID 33298911, 2020).
Intellectual disability (4 papers, 2014 to 2023). "Here we report that PIRM syndrome (ptosis, intellectual disability, retarded growth and mortality) in cattle is associated with an exon skipping mutation in UBE3B and this mutation is present at high frequency in the sample of AI bulls tested." (PMID 25306138, 2014). "Loss-of-function mutations in UBE3B cause severe neurodevelopmental disorders in humans such as developmental delay, intellectual disability and characteristic facial dysmorphisms, e.g., ptosis, blepharophimosis and telecanthus." (PMID 25306138, 2014). "Loss of function mutations within UBE3B have been linked to Kaufman oculo-cerebro-facial syndrome, a rare recessive congenital disorder that is mainly characterized by microcephaly, ocular anomalies, intellectual disability, and distinctive facial features, where hearing loss also has been reported." (PMID 34847940, 2021).
deafness (3 papers, 2022 to 2023). An inherited or acquired condition characterized by the complete loss of the ability to hear from one or both ears. "There were 18 genes linked only to Metabolic hearing loss (including four deafness genes: DMD, DUOX2, CELSR1 and ELMO3) and 54 genes linked only to Sensory hearing loss (including four deafness genes: ARHGAP21, LMO7, UBE3B and ADGRV1)." (PMID 38011198, 2023). "PKHD1L1, DUOX2, CELSR1, ELMO3, ARHGAP21, LMO7 and UBE3B are all defined as deafness genes through work on the mouse orthologues." (PMID 37163093, 2023).
breast carcinoma (2 papers, 2024 to 2025). "Our study uncovers the functional role and regulatory mechanism of UBE3B in breast cancer progression, providing a potential diagnostic biomarker and therapeutic target for breast cancer." (PMID 38914543, 2024). "However, the mechanism underlying the upregulation of UBE3B protein levels in breast cancer remains unexplored." (PMID 38914543, 2024). "Collectively, these findings demonstrate that K286 and K427 are key sites for VHL-mediated UBE3B ubiquitination in breast cancer cells." (PMID 38914543, 2024). "Collectively, VHL suppresses breast cancer cell proliferation, survival, and invasion, at least partially, by inhibiting UBE3B." (PMID 38914543, 2024). "To explore the potential relevance of VHL and UBE3B in human breast cancer, we extracted cell lysates from breast tumors and adjacent normal breast tissues for western blotting." (PMID 38914543, 2024). "To further illustrate that VHL hinders the oncogenic potential of breast cancer cells through its regulation of UBE3B, we depleted UBE3B in MDA-MB-231 and T47D cells following VHL ablation (referred to as VHL-KD#1+UBE3B-KD)." (PMID 38914543, 2024). "Next, we assessed the effect of VHL on the UBE3B-HIF-2α axis-mediated breast cancer cell proliferation, survival, and invasion." (PMID 38914543, 2024). "To elucidate the mechanism by which UBE3B protein levels are upregulated in breast cancer, we scrutinized the published liquid chromatography-tandem mass spectrometry (LC-MS/MS) data obtained from MDA-MB-231 cells stably expressing Flag-UBE3B." (PMID 38914543, 2024). "In addition, we showed that UBE3B overexpression robustly attenuates VHL’s inhibitory effects on breast cancer cell proliferation, colony formation, and invasion in vitro, and breast tumor growth and lung metastasis in mice." (PMID 38914543, 2024). "Our current findings uncovered that VHL is a bona fide E3 ligase for UBE3B in breast cancer." (PMID 38914543, 2024). "Taken together, VHL regulates UBE3B protein stability in breast cancer cells." (PMID 38914543, 2024). "Together, these results suggest that VHL may regulate UBE3B protein stability in breast cancer cells." (PMID 38914543, 2024). "UBE3B, identified as an oncoprotein, exhibits elevated protein levels in breast cancer." (PMID 38914543, 2024). "Moreover, our recent findings indicate that UBE3B promotes breast cancer growth and metastasis by counteracting VHL-mediated HIF-2α degradation." (PMID 38914543, 2024). "Therefore, UBE3B emerges as a potential therapeutic target in breast cancer." (PMID 38914543, 2024). "Therefore, the development of VHL-based PROTACs targeting UBE3B may offer potential benefits for breast cancer patients." (PMID 38914543, 2024). "Taken together, VHL promotes UBE3B and subsequent HIF-2α degradation and consequently inhibits the oncogenic potential of breast cancer cells." (PMID 38914543, 2024). "VHL promotes the ubiquitination and degradation of UBE3B, which stabilizes the oncoprotein HIF-2α in breast cancer." (PMID 38914543, 2024). "To further precisely outline the expression patterns of UBE3B and VHL in breast cancer cells, we performed immunostaining in breast cancer tissues." (PMID 38914543, 2024). "As expected, the results showed that about 45% of breast cancer cells displayed a negative correlation between the protein levels of UBE3B and VHL." (PMID 38914543, 2024). "We observed decreased VHL protein levels in tumors, coinciding with upregulated UBE3B protein levels, suggesting a negative correlation between the protein levels of VHL and UBE3B in breast cancer." (PMID 38914543, 2024). "Given the established role of UBE3B as an oncoprotein in breast cancer and its regulation by VHL, we sought to examine whether VHL could inhibit UBE3B-mediated breast cancer cell proliferation, survival, and invasion." (PMID 38914543, 2024).
breast carcinoma (continued). "Furthermore, VHL-mediated UBE3B downregulation in breast cancer cells could be restored by the proteasome inhibitor MG132, indicating that VHL modulates UBE3B protein levels through the proteasomal system." (PMID 38914543, 2024). "Importantly, the protein levels of UBE3B and VHL exhibit a negative correlation in breast cancer tissues." (PMID 38914543, 2024). "Additionally, the protein levels of UBE3B and VHL exhibit a negative correlation in breast cancer tissues." (PMID 38914543, 2024).
Hearing impairment (2 papers, 2021 to 2023). A decreased magnitude of the sensory perception of sound. "Mice with a disrupted Ube3b gene display mild hearing impairment at all frequencies at 3 months old, and this impairment was more severe when tested at 6 months old." (PMID 38011198, 2023).
Intellectual-Disability Syndrome (2 papers, 2014 to 2018). "Mutation of UBE3B, an E3 ubiquitin ligase, has been found to lead to Blepharophimosis-Ptosis-Intellectual-Disability Syndrome (BPID) in human infants, indicating potential involvement of UBE3B in the regulation of neuronal signaling in the brain." (PMID 32550383, 2018).
anemia (1 paper, 2021). A reduction in the number of red blood cells, the amount of hemoglobin, and/or the volume of packed red blood cells. "Also in the signature were genes encoding the DNA glycosylase NEIL3, Fanconi Anemia factors (FANCD2, UBE2T), the ubiquitin protein ligase UBE3B, and two specialized DNA polymerases, POLM and POLQ, involved in the non-homologous end-joining (NHEJ) pathways of DSB repair." (PMID 34067180, 2021).
autism (1 paper, 2019). Persistent deficits in social interaction and communication and interaction as well as a markedly restricted repertoire of activity and interest as well as repetitive patterns of behavior. "Genes associated with autism, such as UBE3B and ZNF18, are transcriptionally regulated by membrane depolarization and are involved in experience-dependent learning and synaptic plasticity." (PMID 30867066, 2019).
breast tumor (1 paper, 2024). "The K286/427R mutation of UBE3B dramatically abolishes the inhibitory effect of VHL on breast tumor growth and lung metastasis." (PMID 38914543, 2024). "Taken together, these data convincingly demonstrate that VHL inhibits breast tumor growth and metastasis by promoting UBE3B degradation." (PMID 38914543, 2024). "As anticipated, Flag-VHL led to decreased spontaneous breast tumor growth, a phenomenon effectively counteracted by Myc-UBE3B." (PMID 38914543, 2024). "Collectively, these results indicate that VHL inhibits UBE3B-mediated breast tumor growth and lung metastasis in mice." (PMID 38914543, 2024). "In summary, these findings indicate that VHL suppresses breast tumor growth and lung metastasis by inhibiting UBE3B." (PMID 38914543, 2024). "Our next objective was to investigate VHL’s role in UBE3B-mediated breast tumor growth and metastasis in vivo." (PMID 38914543, 2024). "Recently, we demonstrated that UBE3B promotes breast tumor growth and metastasis by stabilizing HIF-2α stability without affecting its mRNA levels." (PMID 38914543, 2024). "In the present study, we identified UBE3B as a bona fide VHL substrate in breast tumors." (PMID 38914543, 2024). "VHL-mediated UBE3B degradation suppresses breast tumor growth and metastasis." (PMID 38914543, 2024). "Importantly, the protein levels of VHL and UBE3B have a negative correlation in breast tumors." (PMID 38914543, 2024).
developmental disability (1 paper, 2014). Disorders in which there is a delay in development based on that expected for a given age level or stage of development. "Also some phenotypes that might not be associated with RASopathies could be explained by the contribution of the other critical genes in the duplicated region, i.e. severe developmental disability and ocular anomalies could be caused by UBE3B, and brachydactyly could be explained by TRVP4." (PMID 24739123, 2014).
glioblastoma (1 paper, 2024). The most malignant astrocytic tumor (WHO grade IV). "Previous studies have demonstrated that UBE3B depletion significantly suppresses glioblastoma cell proliferation and survival and sensitizes these cells to the anticancer drug TMZ." (PMID 38914543, 2024).
Hypocholesterolemia (1 paper, 2014). An decreased concentration of cholesterol in the blood. "In addition UBE3B is connected with total cholesterol in plasma and importantly UBE3B lesions in human and mouse are associated with hypocholesterolemia." (PMID 25306138, 2014).
Rett syndrome (1 paper, 2024). A severe neurodevelopmental disorder affecting the central nervous system. "Among these, UBE3B was predominantly increased in patients with Rett syndrome and exhibited a strong correlation with the clinical severity score, indicating the severity of the disease." (PMID 39457485, 2024).
schizophrenia (1 paper, 2025). A major psychotic disorder characterized by abnormalities in the perception or expression of reality. "Some studies have found a decrease in mRNAs of ubiquitin ligases such as UBE3B and FBXW7, while other studies of ubiquitin ligase proteins found decreases in the amounts of UBE3B, FBXL21, and MDM2 in the dorsolateral prefrontal cortex of subjects with schizophrenia." (PMID 39940735, 2025).
vascular malformation (1 paper, 2021). A non-neoplastic disorder that is the result of defects of vascular morphogenesis. "Assuming a spontaneous de novo mutation event, one of the identified variants found in the PREX1, UBE3B, PCDHGA2, and ZSWIM6 genes may represent a possible candidate pathogenic variant for this rare form of vascular malformation." (PMID 33652974, 2021).
cancer (3 papers, 2020 to 2025). A tumor composed of atypical neoplastic, often pleomorphic cells that invade other tissues. "Accumulating evidence suggests that UBE3B plays a crucial role in cancer progression and drug resistance." (PMID 38914543, 2024). "Identifying the potential E3 ligase (s) promoting HIF-2α degradation, whose activity is antagonized by UBE3B, is crucial to deciphering UBE3B’s functions in cancer." (PMID 38914543, 2024). "However, the regulatory mechanism governing UBE3B itself in cancer remains unexplored." (PMID 38914543, 2024). "In this study, UBE3B is unveiled as a novel substrate of VHL, providing additional therapeutic options for cancer treatment." (PMID 38914543, 2024). "The relationship between UBE3B deregulation and cancer has not yet been reported or validated." (PMID 33298911, 2020).
neurodevelopmental disorder (2 papers, 2014 to 2025). A behavioral and cognitive disorder with onset during the developmental period that involves impaired or aberrant development of intellectual, motor, or social functions. "In contrast, genes downregulated in SMS cortical neurons are involved in anatomical structure and multicellular organism development, including genes implicated in neurodevelopmental disorders (i.e., CHD4, UBE3B, KDM5B, and SETD1B)." (PMID 40882620, 2025).
tumor (2 papers, 2020 to 2024). "These pieces of evidence suggest that UBE3B functions as an oncoprotein or tumor suppressor in a context-dependent manner." (PMID 38914543, 2024). "As expected, the tumor volume and weight were comparable between DKO+2P2A+UBE3B-WT and DKO+2P2A+UBE3B-DM T47D tumors." (PMID 38914543, 2024). "T47D tumor growth was significantly increased when VHL was depleted, and this augmented tumor growth was effectively attenuated by UBE3B ablation." (PMID 38914543, 2024).
infection (1 paper, 2020). The state of being infected such as from the introduction of a foreign agent such as serum, vaccine, antigenic substance or organism. "We examined MYCK427R biological function in the established MYCK427R mutant Raji cells with or without Ad-UBE3B infection." (PMID 33298911, 2020).
UBE3B also shares sentences with these, for which no sentence is quoted: Sensory hearing loss (2 papers); Angelman syndrome (1); autism spectrum disorder (1); autosomal-recessive inherited disorder (1); Blepharophimosis (1); cervical carcinoma (1); developmental delay (1); gastric cancer (1); hepatocellular carcinoma (1); microcephaly (1); myopia (1); non-small cell lung carcinoma (1); osteosarcoma (1); ovarian carcinoma (1); prostate carcinoma (1); ptosis (1); RASopathies (1); telecanthus (1).